TNF (tumor necrosis factor)
Diseases named in the same sentence as TNF in open-access papers (continued):
Sharing a sentence is not in itself a finding about the gene and the disease.
colitis (continued). "Our data suggests that TNF-α target epithelial cells (and perhaps lymphocytes) during the initial phase of colitis to trigger a cytokine network as well as to enhance mucin production." (PMID 21949848, 2011). "TNF-α released from macrophages in the early inflammatory response plays an important role in experimental colitis and it is likely the regulator key of the inflammatory cascade in IBD." (PMID 21931839, 2011). "Our findings are in contrast with a report that shows an exacerbated DSS-induced colitis in TNF-α knockout mice." (PMID 21949848, 2011). "Pro-inflammatory markers including IL(interleukin)-6, IL-1 and TNF(tumor necrosis factor)-alpha are increased in colitis." (PMID 22073943, 2011). "Probiotic administration attenuated development of signs and symptoms of colitis, reduced colonic expression of TNFα, IL-6 and IFNγ and reserved colonic downregulation of PPARγ, PXR and FXR caused by TNBS." (PMID 21829567, 2011). "In conclusion, this study demonstrates for the first time that mucosal TNF-α and alteration of the adherent mucus barrier are predisposing factors for early onset epithelial cells damage in DSS colitis." (PMID 21949848, 2011). "A single dose of TCDD treatment blocked colitis symptoms, corrected weight loss, and reduced systemic expression of IL-17, IFN-γ, MCP-1, exotaxin-1, and TNF-α levels." (PMID 21858153, 2011). "It has been shown that selective blockade of IL-1R, CXCR2, CXCL1/KC, MCP-1, MIP-2, TNF-α and IL-6 significantly decreases severity of colitis and neutrophil/macrophage migration." (PMID 22073270, 2011). "In chronic DSS-induced colitis, both decreased expression of pro-inflammatory cytokines (TNF-α, NO, and IL-1β) and increased anti-inflammatory mediators (IL-10) in the colonic mucosa contributed to attenuate inflammation after Resveratrol treatment." (PMID 21151942, 2010). "In rats with normal blood cholesterol levels, simvastatin was found to ameliorate immunopathology in an acute TNBS colitis model by blocking neutrophil accumulation in the small intestine and lowering serum TNF-α levels." (PMID 21151942, 2010). "A detailed dose-response study and longer treatment durations using other colitis models that are more dependent on TNF elevation should be performed to more accurately assess the potential of LMP-420 for therapy of inflammatory bowel disease." (PMID 18331642, 2008). "Longer term studies using colitis models that are more dependent on TNF elevation should be performed to more accurately assess the potential of LMP-420 for therapy of inflammatory bowel disease." (PMID 18331642, 2008). "Stool levels of TNF in RAG-2-/- mice with severe chronic DSS colitis were 13 ± 6 pg/100 mg stool at the time of tissue collection on day 62, which is statistically similar to pre-DSS levels of 3 ± 1 pg/100 mg stool (p = 0.13)." (PMID 18331642, 2008). "Mice were euthanized after 16 days of treatment to determine colonic TNF content and the histologic severity of colitis." (PMID 18331642, 2008). "These contrasting data suggest that increased investigation will be necessary to clarify the role of TNF in DSS-induced colitis." (PMID 18331642, 2008). "NK cell and neutrophil subsets were compartmentalized in mucosal inductive and/or effector site to further foster adaptive Th1 responses through IFN-γ and IL-12p40 production as well as TNF-α expression during colitis." (PMID 18533024, 2008). "Perhaps the production of CXCR3 ligands along with IFN-γ and TNF-α during colitis progression creates a situation in which Th1 cells are recruited, activated, further differentiated, and expanded to initiate or maintain disease." (PMID 18533024, 2008). "DSS colitis in the VDR KO mice was accompanied by high colonic expression of TNF-α, IL-1 α, IL-1β, IL-12, IFN-γ, IL-10, MIP-1α and KC." (PMID 17397543, 2007).
colitis (continued). "Recently, we have demonstrated, using an experimental model of colitis, that the structure and function of TJs in the intestinal epithelial is dependent of the production of proinflammatory cytokines (e.g. TNF-α)." (PMID 17971210, 2007). "Examining the expression of cytokines, we found significantly elevatedmRNA levels of proinflammatory cytokines IL-1β, IL-6, GM-CSF, and TNFα in micewith TNBS-induced colitis." (PMID 18288268, 2007). "We have shown in the present article that in vivo expression of the novel cytokine hIL-32 induced TNFα production, and that overexpressed IL-32β significantly exacerbated the mouse model of arthritis and colitis." (PMID 17078892, 2006). "The murine model of IBD, trinitrobenzen sulfonic acid (TNBS)-induced colitis, is exacerbated in TNFα transgenic mice, and is ameliorated in tumor necrosis factor receptor 2-knockout mice." (PMID 17078892, 2006). "In the present study, we also demonstrated that the in vivo overexpression of hIL-32β resulted in the exacerbation of other mouse models of TNFα-related diseases – collagen-induced arthritis and hapten-induced colitis." (PMID 17078892, 2006). "We examined the in vivo relationship between IL-32 and TNFα, and the pathologic role of IL-32 in the TNFα-related diseases – arthritis and colitis." (PMID 17078892, 2006). "In vivo expressed IL-32 was therefore supposed to play an important role in the exacerbation of colitis, in part through the TNFα-inducing effect." (PMID 17078892, 2006). "In a DSS-induced murine model of colitis, matrine treatment mitigated disease symptoms, reduced key inflammatory markers (IL-1β, TNF-α, IL-6) and oxidative stress indicators (including ROS), and restored bile acid homeostasis by upregulating transporters (MRP3 and MRP4) and bile acid receptor FXR." (PMID 41882686, 2026). "Additionally, AhR∆IEC colitis mice showed significantly higher levels of mRNA expression of proinflammatory cytokines IL‐1β, IFNγ, and TNFα in colonic mucosa when compared to WT mice with colitis." (PMID 40410944, 2025). "It has been reported that, in DSS-induced colitis models, ginger-derived nanoparticles were found to be predominantly absorbed by intestinal epithelial and immune cells, decreasing pro-inflammatory cytokines (TNF-α, IL-6), and improving barrier function." (PMID 41383462, 2025). "TNF-α levels increased significantly in AA-induced colitis compared to the control group (p<0.01)." (PMID 40656621, 2025). "Therapy with nicotine reduced TNF production in the colon and improved colitis, but subdiaphragmatic vagotomy of the ventral and dorsal vagus nerves raised the colitis disease activity score and markedly elevated TNF, IL-6, and IL-1b production in colon tissue." (PMID 39828740, 2025). "The synbiotic FCT (fermented milk with L. gasseri 505 and C. tricuspidata) has demonstrated concurrent upregulation of MUC2, TFF3, and tight junction proteins (occludin, ZO-1), along with significant downregulation of TNF-α, IFN-γ, IL-1β, IL-6, and iNOS/COX-2 in colitis-associated cancer models." (PMID 41395459, 2025). "Similarly, elevated TNF-α levels in DSS-induced colitis exacerbate epithelial damage and intestinal permeability." (PMID 40502390, 2025). "The in vitro treatment of colonic biopsies from DSS-induced colitis mice with RvD2 (0.01, 0.1, and 0.3 μM) or anti-TNFα resulted in a significant downregulation of the pro-inflammatory cytokine transcripts TNFα and IL6, suggesting a marked attenuation of colonic inflammation." (PMID 40649782, 2025). "Collectively, these results provide a solid experimental foundation indicating that suramin may effectively alleviate acute colitis by suppressing the TNF-α/NET/PTX3 axis and reducing ROS-mediated tissue injury." (PMID 40428786, 2025).
colitis (continued). "The European Crohn’s and Colitis Organization (ECCO) also recommends the use of anti-TNF as the first-line therapy in moderate-to-severe Crohn’s disease while reserving the use of vedolizumab in patients with inadequate response to anti-TNF therapy." (PMID 40624415, 2025). "Interestingly, PPT with an anti-inflammatory effect (e.g., suppression of IL-6, IL-1β, and TNF-α) ameliorated colitis, resulting in the recovery of body weight and colon length." (PMID 40141242, 2025). "Furthermore, they exhibit immunomodulatory effects by suppressing pro-inflammatory cytokines such as TNF-α and IL-6 in LPS-stimulated macrophages and colitis-induced mice." (PMID 40509414, 2025). "Similarly, in a study involving mice with DSS-induced colitis, Bifidobacterium pseudolongum was found to reduce the mRNA expression levels of pro-inflammatory cytokines (IL-1β, IL-6, IL-10, and TNF-α)." (PMID 40299512, 2025). "Also, ELISA results showed that markers of M1 macrophages (iNOS, IL-6, TNF-α) in colon tissue increased significantly during the colitis stage." (PMID 40370742, 2025). "Our functional data show that DSS-colitis increases the number of active nodose ganglia neurons at baseline, possibly owing to altered membrane excitability, with a reduction in the amplitude of cytokine-specific responses (TNF and IL-10)." (PMID 40268933, 2025). "This study investigates whether Lactobacillus murinus (L. murinus) attenuates tumor necrosis factor alpha (TNF-α)-induced pro-inflammatory responses in a human intestinal epithelial cell model of colitis by modulating the aryl hydrocarbon receptor (AHR)." (PMID 41373818, 2025). "Xia’s research on Lacticplantibacillus plantarum for alleviating colitis found that this probiotic inhibits the expression of MyD88 and NF-kB/p65 signaling pathways and reduces pro-inflammatory factor TNF-α levels, which is consistent with the findings of this study." (PMID 40005605, 2025). "In fact, patients with colitis had elevated levels of IL-1β, IL-6, and TNF-α." (PMID 40238292, 2025). "Additionally, as the results confirm the presence of IL-6 and TNF-α in the serum of the DSS-induced colitis mouse model, KMLE reduced the cytokines in the serum of the DSS-induced colitis mouse model." (PMID 40227441, 2025). "It was shown that the inhibition of enhancer of zest homolog 2 (Ezh2), a major histone methyltransferase, promoted the differentiation of hematopoietic progenitor cells (HPCs) into MDSCs by activating the Janus kinase (JAK)-STAT and TNF signaling pathways in DSS-induced colitis." (PMID 40244120, 2025). "Combinational therapy involving anti‐TNF‐α and crotonate can significantly ameliorate colitis." (PMID 40650658, 2025). "Furthermore, the present study’s findings revealed that Helicobacter typhlonius was the species most severely influenced by BA in the experiment, and that it is a major illness trigger that encourages colitis by producing excessive amounts of TNF-α." (PMID 40977701, 2025). "Additionally, PPE can alleviate inflammatory symptoms of colitis and reduced serum levels of the inflammatory markers (TNF-α, IL-6, and CRP) owing to its anti-inflammatory properties." (PMID 40359212, 2025). "Shi and colleagues demonstrated that treatment with N-acetyl-seryl-aspartyl-lysyl-proline (AcSDKP) played a protective role in experimental colitis and suppressed TNF-α-induced inflammatory responses of IECs by inhibiting the activation of the MEK/ERK signaling pathway." (PMID 40362525, 2025). "The untreated acetic acid-induced colitis rats presented increased serum IL-6 and TNF-α." (PMID 40430512, 2025). "In vivo, intestinal epithelial cell‐specific knockout of ATF7 or PINK1 exacerbated dextran sulfate sodium‐induced colitis, with greater epithelial injury, elevated cytokine production, and transcriptional activation of TNF, NF‐kappaB, and inflammatory bowel disease signalling pathways." (PMID 40903840, 2025).
colitis (continued). "Sini decoction inhibits the onset and progression of colitis-associated colon cancer in mice by upregulating the numbers of A. muciniphila, Bifidobacterium in the intestine, and CD8+ T cells, while downregulating CD4+ T cells, IL-6, and TNF-α." (PMID 40028328, 2025). "Notably, colitis mice exhibited increased serum IL-6 and colonic TNF-α concentrations in contrast with the CON group." (PMID 39857378, 2025). "Indeed, it has been demonstrated in the literature that α-linolenic acid can reduce the inflammatory state of colitis by down-regulating the mRNA levels of several pro-inflammatory genes, such as IL-6, cyclooxygenase 2, and tumor necrosis factor α." (PMID 40286023, 2025). "APN also reduces TNF-α secreted by macrophage and anti-TNF-α drugs have become clinical drugs for IBD for its activities on inhibit the progression of colitis-related colon cancer, so APN and its receptor agonists are expected to become one of clinical treatment strategies for IBD." (PMID 40713669, 2025). "After establishing an in vitro colitis model by stimulating Caco-2 cells with TNF-α, we investigated whether AHR could be modulated by its well-defined exogenous and endogenous ligands in this system." (PMID 41373818, 2025). "This study evaluated the immunomodulatory potential of resolvin D2 (RvD2), a pro-resolving lipid mediator, using a murine model of colitis and the ex vivo treatment of intestinal mucosal biopsies from CD patients, comparing its effects to those of conventional anti-TNFα therapy." (PMID 40649782, 2025). "Our study showed that PA improved colitis in mice, as evidenced by improvements in disease-related indicators, including weight loss, DAI scores, pathological manifestations, and levels of pro-inflammatory mediators (IL-1β, IL-6, TNF-α)." (PMID 40969742, 2025). "It was shown that increased O-linked N-acetylglucosamine modification (O-GlcNAcylation) of STAT3 upregulated the expression of proinflammatory cytokines such as IL-6, IL-1β, and TNF-α, while downregulating the level of the anti-inflammatory cytokine IL-10 and aggravating colitis in mice." (PMID 40078988, 2025). "Moreover, CCL20, TNF-α and COX-2 were likely to play facilitative roles because they had been implicated in the pathogenesis of DSS-induced colitis and human IBDs43,51–55." (PMID 41290870, 2025). "However, the detection of the barrier protein Occludin and inflammatory factors TNF-α and IL-1β indicate the occurrence of colitis in the DSS + ABX mice." (PMID 40647020, 2025). "In models of acute or systemic inflammation, including carrageenan-induced pleurisy, nociception and paw edema, and DSS-induced colitis, treatment decreased leukocyte migration, Th1/Th17 polarization, levels of pro-inflammatory cytokines (IL-6, TNF-α, IFN-γ) and increased IL-10." (PMID 41470797, 2025). "Moreover, dual targeting of cytotoxic T-lymphocyte-associated protein 4 (CTLA-4) and PD-1, alongside clinically available TNF inhibitors, enhances macrophage depletion and prevents colitis and hepatitis in vivo." (PMID 40725144, 2025). "Moreover, dietary resveratrol attenuated the inflammatory status and down-regulated the expression of proinflammatory cytokines such as IL-2, IFN-γ, IL-1β, IL-6, and TNF-α in colitis mouse model." (PMID 40078988, 2025). "Deletion of EGFR in macrophages in DSS-colitis mice leads to the increase of anti-inflammatory cytokines, such as IL-10 that inhibits the release of proinflammatory cytokines such as IL-6, IL-8 and TNF, limiting colitis development." (PMID 39966897, 2025). "For example, it has been demonstrated to possess a spectrum of anti-colitis effects, such as upregulating beneficial metabolites, downregulating pro-inflammatory cytokines (TNF-α and IL-6), restoring the intestinal mucosal barrier, and enhancing the host’s resistance to DSS-induced UC." (PMID 40002063, 2025).
colitis (continued). "Experimental validation confirmed synergistic effects between MS.275 and TNF-α inhibitors in DSS-induced colitis, significantly improving disease activity indices, colon length preservation, and restoring signature gene expression patterns through immunohistochemical analysis." (PMID 40821793, 2025). "Research has revealed that Helicobacter_typhlonius infection could evoke excessive production of TNF‐α, a key disease trigger that promotes the progression of colitis." (PMID 40501499, 2025). "We hypothesized that TAPS would allow us to deliver the monoclonal anti-TNFα antibody etanercept to the colon and thereby treat colitis in a rat model of the disease." (PMID 40366696, 2025). "It has been reported that Houttuynia Chordata, a traditional medicinal plant, decreased inflammatory cytokines, such as IL-6 and TNF-α, and increased the level of anti-inflammatory IL-10 and various tight junction proteins in a dextran sulfate sodium-induced colitis model." (PMID 40149930, 2025). "In conclusion, DBK successfully reduced inflammation in DSS-induced UC mice by modulating the IL-6/IL-6R and IL-17A/IL-17RA pathways, as evidenced by alleviated colitis symptoms, decreased pro-inflammatory cytokines (TNF-α, IL-6, IL-1β), and histological improvements." (PMID 40005956, 2025). "Moreover, given the intense inflammatory response characterizing colitis, we examined the gene expressions related to inflammation in colon tissue, including tumor necrosis factor α (TNF-α), interleukin-6 (IL-6), and interleukin-1β (IL-1β)." (PMID 40000617, 2025). "Connectivity Map analysis identified MS.275 as the top therapeutic enhancer, with experimental validation in DSS-induced colitis confirming synergistic anti-inflammatory effects with TNF-α inhibitors, improving disease activity indices and restoring signature gene expression patterns." (PMID 40821793, 2025). "These Ly6Chi monocytes-derived DCs exacerbated DSS-induced colitis by secreting TNF-α." (PMID 40244120, 2025). "Similarly, QA has been shown to lower IL-1β, iNOS, IL-6, and TNF-α expression in a mouse colitis model." (PMID 40538727, 2025). "By suppressing this pathway, MP may reduce the production of pro-inflammatory cytokines, such as IL-1β, TNF-α, and IL-6, thereby alleviating colitis symptoms." (PMID 40012624, 2025). "Moreover, our DSS-induced colitis mice increased the levels of proinflammatory cytokines including IL-1β, TNF-α, IFN-γ, IL-17, and IL-18, which have been shown to increase in IBD patients." (PMID 40224484, 2025). "In 2,4-dinitrobenzene sulfonic acid (DNBS)-induced colitis, treatment with verbascoside improved macroscopic damage, body weight, and inflammatory markers (TNF-α, IL-1β) while reducing oxidative stress and metalloproteinase activity (MMP-2 and MMP-9) in colon tissue." (PMID 40724000, 2025). "Interestingly, TNF inhibition dramatically improved survival rates (90%) and alleviated both colitis and systemic inflammation in our preclinical AIFEC model." (PMID 41116055, 2025). "In a mouse model of colitis, treatment with Frondanol significantly reduced colonic inflammation and levels of inflammatory cytokines such as tumor necrosis factor (TNF)-α, interleukin (IL)-6, and IL-1β, indicating its potential anti-inflammatory action in the gut lining." (PMID 41304959, 2025). "Empirical evidence has demonstrated that the Src inhibitor dasatinib exacerbates colitis by elevating TNF‐α levels, which occurs through the suppression of IL‐10, possibly involving the activation of the Src‐Akt signaling pathway to facilitate IL‐10 production." (PMID 40895135, 2025). "We found that oral administration of IPA attenuated mucosal inflammation in both acute and chronic colitis models in mice, as characterized by increased body weight, and reduced levels of pro-inflammatory cytokines (e.g. TNF-α, IFN-γ, and IL-17A) and histological scores in the colon." (PMID 39956891, 2025).